CDK9 (cyclin dependent kinase 9)
Description:
Protein kinase involved in the regulation of transcription. Member of the cyclin-dependent kinase pair (CDK9/cyclin-T) complex, also called positive transcription elongation factor b (P-TEFb), which facilitates the transition from abortive to productive elongation by phosphorylating the CTD (C-terminal domain) of the large subunit of RNA polymerase II (RNAP II) POLR2A, SUPT5H and RDBP. This complex is inactive when in the 7SK snRNP complex form. Phosphorylates EP300, MYOD1, RPB1/POLR2A and AR and the negative elongation factors DSIF and NELFE. Regulates cytokine inducible transcription networks by facilitating promoter recognition of target transcription factors (e.g. TNF-inducible RELA/p65 activation and IL-6-inducible STAT3 signaling). Promotes RNA synthesis in genetic programs for cell growth, differentiation and viral pathogenesis. P-TEFb is also involved in cotranscriptional histone modification, mRNA processing and mRNA export. Modulates a complex network of chromatin modifications including histone H2B monoubiquitination (H2Bub1), H3 lysine 4 trimethylation (H3K4me3) and H3K36me3; integrates phosphorylation during transcription with chromatin modifications to control co-transcriptional histone mRNA processing. Also catalyzes phosphorylation of histone H1.4 (H1-4) at Ser-187' (H1.4S187Ph), a modification associated with transcription activation. The CDK9/cyclin-K complex has also a kinase activity towards CTD of RNAP II and can substitute for CDK9/cyclin-T P-TEFb in vitro. Replication stress response protein; the CDK9/cyclin-K complex is required for genome integrity maintenance, by promoting cell cycle recovery from replication arrest and limiting single-stranded DNA amount in response to replication stress, thus reducing the breakdown of stalled replication forks and avoiding DNA damage. In addition, probable function in DNA repair of isoform 2 via interaction with KU70/XRCC6. Promotes cardiac myocyte enlargement. RPB1/POLR2A phosphorylation on 'Ser-2' in CTD activates transcription. AR phosphorylation modulates AR transcription factor promoter selectivity and cell growth. DSIF and NELF phosphorylation promotes transcription by inhibiting their negative effect. The phosphorylation of MYOD1 enhances its transcriptional activity and thus promotes muscle differentiation. Catalyzes phosphorylation of KAT5, promoting KAT5 recruitment to chromatin and histone acetyltransferase activity.
Synonyms: CDC2L4; TAK; PITALRE; C-2k; CTK1
Tractability: Small molecule: a drug acting on it is in phase 2 or 3 trials; a structure with a bound ligand is known; a high-quality ligand is known; it has a high-quality binding pocket; it belongs to a druggable protein family. PROTAC: it is named in the literature on targeted protein degradation; UniProt records ubiquitination sites on it; ubiquitination databases record sites on it; its protein half-life has been measured; a small molecule that binds it is known.
Target class: Enzyme; CMGC protein kinase group; Protein Kinase; CMGC protein kinase CDK9 subfamily; Kinase; CMGC protein kinase CDK family
Chemical probes: NVP-2 (high quality), THAL-SNS-032 (high quality)
Gene: Protein-coding gene on chromosome 9 (127,785,679 to 127,790,792, forward strand). Ensembl gene ENSG00000136807.
Subcellular location: Nucleus; Cytoplasm; Nucleus, PML body
Subcellular location (Human Protein Atlas): Nucleoplasm; Cytoplasmic bodies
Pathways (Reactome):
Disease: Formation of HIV elongation complex in the absence of HIV Tat; Formation of HIV-1 elongation complex containing HIV-1 Tat; HIV elongation arrest and recovery; Interactions of Tat with host cellular proteins; Pausing and recovery of HIV elongation; Pausing and recovery of Tat-mediated HIV elongation; Tat-mediated HIV elongation arrest and recovery; Tat-mediated elongation of the HIV-1 transcript
Gene expression (Transcription): Formation of RNA Pol II elongation complex; RNA Polymerase II Pre-transcription Events; RNA Polymerase II Transcription Elongation; RNA polymerase II transcribes snRNA genes
Signal Transduction: Estrogen-dependent gene expression; SMAD2/SMAD3:SMAD4 heterotrimer regulates transcription
Gene Ontology:
Molecular function: 7SK snRNA binding; cyclin-dependent protein serine/threonine kinase activity; DNA binding; histone H1-4S187 kinase activity; kinase activity; protein binding; protein serine kinase activity; protein serine/threonine kinase activity; RNA polymerase II CTD heptapeptide repeat kinase activity; transcription coactivator binding; transcription elongation factor activity; chromatin binding; protein kinase activity; ATP binding; protein kinase binding; RNA polymerase II cis-regulatory region sequence-specific DNA binding; snRNA binding; transcription cis-regulatory region binding
Biological process: cellular response to cytokine stimulus; host-mediated activation of viral transcription; negative regulation of protein localization to chromatin; nucleus localization; positive regulation of protein localization to chromatin; positive regulation of transcription by RNA polymerase II; positive regulation of transcription elongation by RNA polymerase II; protein phosphorylation; regulation of cell cycle; regulation of DNA repair; regulation of mitotic cell cycle; regulation of mRNA 3'-end processing; regulation of muscle cell differentiation; replication fork processing; transcription by RNA polymerase II; transcription elongation by RNA polymerase II; transcription elongation-coupled chromatin remodeling; cell population proliferation; transcription initiation at RNA polymerase II promoter
Cellular component: cyclin/CDK positive transcription elongation factor complex; membrane; nucleus; P-TEFb complex; PML body; transcription elongation factor complex; cyclin-dependent protein kinase holoenzyme complex; nucleoplasm; cytoplasm
Genetic constraint (gnomAD): Loss-of-function variants: 29 observed, 34.73 expected, observed/expected ratio (o/e) 0.84, 90% interval 0.62 to 1.14. The upper end of that interval is the gene's LOEUF score, 1.14, which puts it in group 4 of 6, group 1 being the genes least tolerant of losing a copy. Missense variants: 363 observed, 502.64 expected, observed/expected ratio (o/e) 0.72, 90% interval 0.66 to 0.79. Synonymous variants: 230 observed, 198.41 expected, observed/expected ratio (o/e) 1.16, 90% interval 1.04 to 1.29.
Homologues: Orthologues: chimpanzee CDK9 (100% identical), macaque CDK9 (100% identical), pig CDK9 (99% identical), mouse Cdk9 (99% identical), rat Cdk9 (99% identical), dog CDK9 (98% identical), guinea pig Cdk9 (98% identical), tropical clawed frog cdk9 (91% identical), zebrafish cdk9 (90% identical), Drosophila melanogaster Cdk9 (71% identical), Caenorhabditis elegans cdk-9 (54% identical). Paralogues in human: CDK12 (45% identical), CDK13 (44% identical), CDK16 (34% identical), CDK18 (33% identical), CDK20 (33% identical), CDK7 (32% identical), CDK10 (32% identical), CDK11A (31% identical), CDK11B (31% identical), CDK2 (31% identical), CDK1 (31% identical), CDK3 (31% identical), and 14 more.
Diseases named in the same sentence as CDK9 in open-access papers:
CDK9 is named in the same sentence as 190 diseases in open-access papers, as found by Europe PMC text mining. Sharing a sentence is not in itself a finding about the gene and the disease. The quoted sentences say what the papers report.
breast carcinoma (53 papers, 2008 to 2026). "Estrogen positive breast cancer cells were found to be very sensitive to CDK9 inhibitors and at a sub-nanomolar concentration of CDK9 inhibitor, the cell undergoes apoptosis associated with a several-fold downregulation of c-MYB expression." (PMID 36046384, 2020). "Cyclin-dependent kinase 9 (CDK9) is often dysregulated in breast cancer, and its deficiency results in genomic instability." (PMID 30405916, 2018). "Using the NKI dataset we found high-CDK9 expression was associated with significantly worse metastasis-free survival rates in breast cancer patients." (PMID 30647871, 2018). "We found that elevated CDK9 expression was associated with decreased progression-free survival in breast cancer patients and a worse overall survival among patients with TNBC." (PMID 30647871, 2018). "Similarly, the high expression of cyclin T1 correlated with an improved disease-free survival of patients with stomach adenocarcinoma and high CDK9 expression was associated with prolonged survival in breast cancer." (PMID 36979907, 2023). "Recent data have demonstrated that also broad-spectrum CDK inhibitors with potent activity against CDK9 are effective at inhibiting the growth of cancer cells, including breast cancer." (PMID 41505030, 2026). "Investigations into CDK9’s role in promoting drug resistance in breast cancer are rapidly expanding." (PMID 40949156, 2025). "We have demonstrated that CDK9 inhibitor AZD4573 exhibits the anti-tumor effect on breast cancer cells, inducing cell death through the accumulation of DNA damage caused by persistent T-R conflicts." (PMID 40713627, 2025). "Higher CDK9 expression was found to correlate with shorter OS, suggesting its significant role in breast cancer progression and poorer prognosis." (PMID 40713627, 2025). "Dinaciclib, a drug that targets CDK1, CDK2, CDK5, and CDK9, has demonstrated efficacy in the treatment of breast cancer by reducing the expression of stem cell markers and decreasing cancer cell viability." (PMID 40004024, 2025). "AZD4573 treatment resulted in decreased phosphorylation of RNAP2 in both sensitive and less-sensitive cell lines, suggesting that AZD4573 successfully inhibits CDK9 activity in breast cancer cell lines." (PMID 40713627, 2025). "This led us to investigate the role of CDK9 in breast cancer, focusing on its potential for therapeutic intervention." (PMID 40713627, 2025). "We also provide the first RNAPII ChIP-seq data in a breast cancer context that demonstrates genome-wide promoter pausing following inhibition of CDK9." (PMID 38001268, 2024). "Although the efficacy of CDK7 inhibition in endocrine-resistant, palbociclib-resistant breast cancer is currently being investigated, little is known as to the potential of targeting the transcriptional regulator CDK9 in ER+ breast cancers." (PMID 37801608, 2024). "Two studies have identified leads to disrupt CDK9/Cyclin T interactions and demonstrate activity against breast cancer cells." (PMID 37111276, 2023). "CDK9 is reported to have a role in the proliferation and progression of several solid tumors such as colorectal, hepatic, cervical, and breast cancers." (PMID 37298748, 2023). "An increased expression of CDK9 has already been demonstrated in several types of malignancies, such as pancreatic cancer, prostate cancer, lymphoma, and breast cancer." (PMID 36979907, 2023). "These groups reported that transcription elongation through Myb was inhibited in erythroid cells or in breast cancer cells by CDK9 inhibitors." (PMID 37808852, 2023). "Co-immunoprecipitation experiments in MDA-MB-231 breast cancer cells demonstrated that the compound decreased CDK9/Cyclin T interactions." (PMID 37111276, 2023). "The antitumoral activity of a novel CDK9 PROTAC termed THAL-SNS-032 was then explored in a panel of breast cancer cell lines representative of different molecular subgroups." (PMID 35628286, 2022).
breast carcinoma (continued). "In the present article, we describe the activity of the CDK9 PROTAC THAL-SNS-032 on several in vitro cellular breast cancer models." (PMID 35628286, 2022). "High CDK9 expression level correlates with poor prognosis and drug resistance in several cancer types including with breast cancer, lung cancer, prostate cancer, endometrial cancer, melanoma, osteosarcoma, myeloid leukemia, and soft tissue sarcoma." (PMID 35884401, 2022). "In HR+ advanced breast cancer, upregulated exosomal mRNAs encoding cell cycle-regulated thymidine kinase 1 (TK1) (p = 0.01) and cyclin-dependent kinase 9 (CDK9) (p = 0.03) correlated with poor clinical response to the CDK4/CDK6 inhibitor palbociclib." (PMID 35565189, 2022). "A growing body of evidence suggests that the expression of CDK9 is elevated in malignant cells, such as chronic lymphocytic leukemia, multiple myeloma, breast cancer, and lung cancer cells." (PMID 36313366, 2022). "There is sufficient evidence that supports the role of CDK9 as a molecular target for treatment of a number of malignancies including breast cancer, colorectal cancer, and acute myeloid leukaemia (AML)." (PMID 35890157, 2022). "Most recently, another receptor tyrosine kinase, ALK was shown to promote HR activity and PARPi/platinum resistance through phosphorylating CDK9 at Y19 residue (p-Y19 CDK9) in ovarian and breast cancer." (PMID 36284291, 2022). "at the University of Ulsan claimed the natural products Imidazo[1,2-a]pyrazines 58 and 59 (patent in Korean) as CDK9 inhibitors, with a specific use in breast cancer." (PMID 33632038, 2021). "Although there is a diverse genetic background in breast cancer, alteration in CDK9 expression is one molecular pathway in the development of the disease through its interaction with proto-oncogenes." (PMID 33632038, 2021). "Recently, some studies have shown that CDK9 plays a key role in prostate cancer, breast cancer, acute myeloid leukemia, hepatocellular carcinoma." (PMID 35087760, 2021). "In HR+ breast cancer, elevated circulating exosomal levels of mRNAs encoding cell cycle-regulated thymidine kinase 1 (TK1) and cyclin-dependent kinase 9 (CDK9) were associated with poor clinical response to the CDK4/CDK6 inhibitor palbociclib." (PMID 33322643, 2020). "miR-874 contributes to inhibit tumor angiogenesis through targeting STAT3 in gastric cancer, which can also inhibit cell proliferation and induce apoptosis in human breast cancer by targeting cyclin-dependent kinase 9 (CDK9)." (PMID 32908641, 2020). "Overexpression of the thymidine kinase 1 (TK1) and the cyclin-dependent kinase 9 (CDK9) in plasma-derived exosomes was significantly correlated with clinical resistance to CDK4/6 inhibitors in metastatic breast cancer patients." (PMID 32823947, 2020). "We sought to investigate the relevance of CDK9 targeting in breast cancer cells and the potential therapeutic efficacy of selectively inhibiting CDK9 in TNBC." (PMID 30647871, 2018). "Our data demonstrating that elevated CDK9 expression is associated with worse overall survival and with diminished relapse-free survival, indicate a prognostic significance for CDK9 expression in breast cancer." (PMID 30647871, 2018). "Prior studies have shown that CDK9 mediated transcription regulation of MYC is important in therapy resistance in breast cancer and disease maintenance in hepatocellular carcinoma." (PMID 28404924, 2017). "A number of CDK9 inhibitors (CDK9i) are available and in breast cancer cells, such inhibitors can re-impose the block to MYB transcriptional elongation and suppress MYB expression." (PMID 26812885, 2016). "In endocrine-resistant ERα+ breast cancer, CDK9 mediates hyperphosphorylation of serine-2 in the RNA Pol II CTD at the c-MYC gene promoter, resulting in transcriptional elongation and overexpression of c-MYC, which drives estrogen-independent growth of resistant cancer cells." (PMID 40949156, 2025).
breast carcinoma (continued). "Furthermore, increased CDK9 mRNA expression in plasma-derived exosomes from HR+/HER2-breast cancer patients treated with palbociclib plus hormonal therapy correlates with clinical resistance." (PMID 40949156, 2025). "Moreover, previous studies have suggested a potential prognostic role of CDK9 expression in breast cancer." (PMID 40713627, 2025). "Targeting transcription-associated CDK9 synergizes with CDK4/6 inhibitor to drive tumor regression in multiple models of endocrine- and palbociclib-resistant ER+ breast cancer, which could address the challenge of overcoming resistance in patients." (PMID 37801608, 2024). "Eventually, researchers have discovered a direct relationship between ALK and cyclin-dependent kinase 9 (CDK9) in breast cancer, where ALK phosphorylates CDK9, leading to resistance against Poly(ADP-Ribose) Polymerase (PARP) inhibitors and encouraging homologous recombination repair." (PMID 38397899, 2024). "However, a co-immunoprecipitation experiment with the lead compound in MDA-MB-231 breast cancer cells demonstrated that the CDK9/Cyclin T interaction was disrupted." (PMID 37111276, 2023). "Transcriptomic mapping of CDKs in breast cancer demonstrated that the expression of CDK9 predicted a detrimental outcome in basal-like tumors (HR = 1.51, CI = 1.08–2.11, p = 0.015) and, particularly, in the luminal B subtype with HER2+ expression (HR = 1.82, CI = 1.17–2.82, p = 0.0069)." (PMID 35628286, 2022). "In summary, the potent and efficient antitumoral properties of the CDK9 PROTAC THAL-SNS-032 opens the possibility of using this type of compound in breast cancer only if specifically delivered to cancer cells, particularly in ER/HER2-positive and HER2-resistant tumors." (PMID 35628286, 2022). "In addition, breast cancers have evolved the capability of downregulating a tumor-suppressive microRNA (miRNA), miR-874, which suppresses proliferation by downregulating CDK9 expression." (PMID 34041038, 2021). "Furthermore, in breast cancer, increased expression of miR-874-3p inhibited cell proliferation by suppressing cyclin-dependent kinase 9 (CDK9) protein level." (PMID 33123872, 2021). "A dysregulated CDK9-related pathway has been established as a major component for initiation and/or progression of a number of malignancies, including lymphomas, prostate cancer, breast cancer and others." (PMID 33632038, 2021). "Moreover, high expression of cdc7 and RNA polymerase II Subunit A (POLR2A), the direct target of CDK9, is significantly correlated with poor metastasis-free survival in a cohort of breast cancer patients." (PMID 31262335, 2019). "The results of this study indicate that CDK9 may have a potential role as a prognostic biomarker in patients with breast cancer following NACT." (PMID 30405916, 2018). "CDK9 inhibitors have also been shown to inhibit growth of breast cancer cells and tumors." (PMID 30405916, 2018). "Moreover, abemaciclib is the only inhibitor in this class with activity as a single agent in breast cancer and other solid tumors, suggesting a possible involvement of CDK9 inhibition." (PMID 30647871, 2018). "Taken together these data suggest that MYB regulation of BCL2 underlies the heightened sensitivity of ER+ve compared to ER−ve breast cancer cells to CDK9 inhibition, and that these compounds represent a potential therapeutic for ER+ve breast cancers and possibly other MYB-dependent cancers." (PMID 26812885, 2016). "In addition, CDK7/CDK9 inhibitors have also been evaluated in different stages of clinical trials in breast cancer." (PMID 25990212, 2015). "Another current intriguing exampleis the identification of parvinβ, a focal adhesion protein (lost in breast cancer patients), thatincreases the expression, S84 phosphorylation, and activity of PPARγ1 through cyclin-dependent kinase 9(CDK) and suppressed breast cancer growth in vivo." (PMID 18596912, 2008).